CLEC7A (C-type lectin domain containing 7A)
Description:
Lectin that functions as a pattern recognizing receptor (PRR) specific for beta-1,3-linked and beta-1,6-linked glucans, which constitute cell wall constituents from pathogenic bacteria and fungi. Necessary for the TLR2-mediated inflammatory response and activation of NF-kappa-B: upon beta-glucan binding, recruits SYK via its ITAM motif and promotes a signaling cascade that activates some CARD domain-BCL10-MALT1 (CBM) signalosomes, leading to the activation of NF-kappa-B and MAP kinase p38 (MAPK11, MAPK12, MAPK13 and/or MAPK14) pathways which stimulate expression of genes encoding pro-inflammatory cytokines and chemokines (By similarity). Enhances cytokine production in macrophages and dendritic cells (By similarity). Mediates production of reactive oxygen species in the cell (By similarity). Mediates phagocytosis of C.albicans conidia. Binds T-cells in a way that does not involve their surface glycans and plays a role in T-cell activation. Stimulates T-cell proliferation. Induces phosphorylation of SCIMP after binding beta-glucans (By similarity).
Synonyms: Dectin-1; CD369; BGR; CLECSF12; DECTIN1; hDectin-1; SCARE2; CANDF4
Tractability: Antibody: UniProt places it where antibodies can reach, with high confidence; its Gene Ontology location is reachable by antibodies, with high confidence; UniProt predicts a signal peptide or a membrane-spanning region. PROTAC: ubiquitination databases record sites on it.
Target class: Membrane receptor
Gene: Protein-coding gene on chromosome 12 (10,116,777 to 10,130,258, reverse strand). Ensembl gene ENSG00000172243.
Subcellular location: Cell membrane; Cytoplasm (Isoform 5); Cytoplasm (Isoform 6); Cytoplasm (Isoform 7)
Pathways (Reactome):
Immune System: CLEC7A (Dectin-1) signaling
Gene Ontology:
Molecular function: (1->3)-beta-D-glucan binding; carbohydrate binding; pattern recognition receptor activity; protein binding; MHC protein binding
Biological process: apoptotic signaling pathway; cell recognition; cell surface pattern recognition receptor signaling pathway; cellular response to molecule of fungal origin; detection of fungus; detection of molecule of fungal origin; phagocytosis, recognition; positive regulation of cell maturation; positive regulation of cell migration; positive regulation of cell population proliferation; positive regulation of cytokine production involved in inflammatory response; positive regulation of gene expression; positive regulation of interleukin-1 beta production; positive regulation of interleukin-10 production; positive regulation of interleukin-12 production; positive regulation of interleukin-2 production; positive regulation of interleukin-6 production; positive regulation of interleukin-8 production; positive regulation of lymphocyte activation; positive regulation of monocyte chemotactic protein-1 production; positive regulation of nitric oxide biosynthetic process; positive regulation of phagocytosis; positive regulation of protein-containing complex assembly; positive regulation of respiratory burst; positive regulation of superoxide anion generation; and 23 more
Cellular component: cell surface; cytoplasm; plasma membrane; membrane
Genetic constraint (gnomAD): Loss-of-function variants: 15 observed, 15.87 expected, observed/expected ratio (o/e) 0.95, 90% interval 0.63 to 1.45. The upper end of that interval is the gene's LOEUF score, 1.45, which puts it in group 6 of 6, group 1 being the genes least tolerant of losing a copy. Missense variants: 176 observed, 191.8 expected, observed/expected ratio (o/e) 0.92, 90% interval 0.81 to 1.04. Synonymous variants: 71 observed, 68.22 expected, observed/expected ratio (o/e) 1.04, 90% interval 0.86 to 1.27.
Homologues: Orthologues: chimpanzee CLEC7A (98% identical), macaque CLEC7A (95% identical), pig CLEC7A (73% identical), rabbit CLEC7A (68% identical), dog CLEC7A (61% identical), guinea pig CLEC7A (55% identical), rat Clec7a (55% identical), mouse Clec7a (49% identical), zebrafish si:ch211-170d8.8 (20% identical), Drosophila melanogaster rgn (18% identical), zebrafish si:ch211-193e13.5 (18% identical), Caenorhabditis elegans clec-146 (15% identical), and 2 more. Paralogues in human: OLR1 (32% identical), CLEC12B (26% identical), CLEC1A (26% identical), CLEC1B (25% identical), CLEC9A (23% identical), KLRB1 (22% identical), CLEC12A (22% identical), KLRC1 (22% identical), KLRD1 (21% identical), KLRK1 (20% identical), KLRC2 (20% identical), KLRF1 (20% identical), and 11 more.
Diseases named in the same sentence as CLEC7A in open-access papers:
CLEC7A is named in the same sentence as 224 diseases in open-access papers, as found by Europe PMC text mining. Sharing a sentence is not in itself a finding about the gene and the disease. The quoted sentences say what the papers report.
fungal infection (111 papers, 2008 to 2025). "The essential role of Dectin-1 in initiating an antifungal immune response is illustrated by the increased susceptibility to fungal infections in individuals carrying polymorphisms of CLEC7A." (PMID 37158741, 2023). "The mutations in CLEC7A (SNPs rs3901533, rs7309123, and rs16910527) have been associated with fungal infection susceptibility, and Dectin-1 genetic variation plays a crucial role in fungal infection." (PMID 37238269, 2023). "Of note, these deleterious CLEC7A mutations are enriched in the San population of South Africa, a region where subcutaneous mycoses are common." (PMID 36377664, 2022). "Four women from the same family who were immunodeficient were reported to have the c.714T > G (p.Tyr238Ter) mutation in the CLEC7A gene and fungal infection." (PMID 31207142, 2019). "As a polymorphism in the gene encoding the CLR DECTIN-1 (CLEC7A) has previously been shown to be associated with an increased susceptibility to fungal infections, a first set of comparisons assessed the prevalence of CLEC7A and CARD9 polymorphisms in control individuals and patients with RVVC." (PMID 25295030, 2014). "Meta-analysis results suggest that CLEC7A SNPs may affect profound fungal infection susceptibility." (PMID 37238269, 2023). "CLEC7A (Dectin-1) is a C-type lectin pattern recognition receptor, which initiates immune responses to fungal infection mediated through SYK." (PMID 37986179, 2023). "The key receptor to fungi is Dectin-1 (CLEC7A), which detects β-glucans found in the cell wall of fungi and protects against fungal infections." (PMID 33801133, 2021). "Indeed, dectin-1 (CLEC7A) is a C-type lectin known to be a crucial PRR in host defense against fungal infections." (PMID 41249509, 2025). "During the fungal infection CLRs include Dectin-1 (also known as CLEC7A), Dectin-2 and Mincle expressed on macrophages, dendritic cells or neutrophils play a pivotal role in the recognition of fungal cell wall components such as β-glucans, a-mannans, and glycolipids." (PMID 39471181, 2024). "CLRs, such as dectin-1 (CLEC7A) and dectin-2 (CLEC6A), are the main receptor group mediating antifungal recognition, and loss of their shared signalling adaptor molecule, CARD9, results in heightened susceptibility to fungal infections." (PMID 37905492, 2023). "The importance of Dectin-1 for controlling fungal infections was confirmed by the discovery of a premature stop codon polymorphism in human Dectin-1 (CLEC7A), which was identified in a family with a high prevalence of mucocutaneous candidiasis and onychomycosis." (PMID 31242262, 2019). "Additionally, Dectin-1 (Clec7a) and TLR2 important PRRs in PCM and others mycosis were also observed with a transcript expression in the granuloma." (PMID 37868350, 2023).
colitis (73 papers, 2012 to 2026). Inflammation of the colon. "Knockout of the CLEC7A gene, which encodes Dectin-1, results in heightened susceptibility to chemically induced colitis due to altered responses to resident fungi." (PMID 40284630, 2025). "Dectin-1-deficient (Clec7a−/−) mice exhibited more severe experimentally colitis than wild-type mice." (PMID 40820365, 2025). "In Clec7a−/− mice, loss of Dectin-1 (a fungal sensor) leads to Candida overgrowth and exacerbates colitis, directly linking impaired antifungal immunity to inflammation." (PMID 40820365, 2025). "Mice lacking Dectin-1 exhibited increased susceptibility to chemically-induced colitis because of altered responses to indigenous fungi; Dectin-1 gene polymorphism (CLEC7A) in humans is significantly associated with a severe form of UC." (PMID 37191444, 2023). "C-Type Lectin domain containing 7A (CLEC7A) is the gene that directly encodes Dectin-1 and has been associated with colitis." (PMID 34593025, 2021). "Indeed, DECTIN-1–deficient mice (Clec7a−/−) exhibit heightened susceptibility to chemically induced colitis, while human polymorphisms in the DECTIN-1 gene (CLEC7A) are strongly associated with ulcerative colitis." (PMID 38055819, 2023). "Interestingly, concomitant fluconazole treatment reduced the colitis severity, whereas human variants in the Dectin-1 gene CLEC7A have been associated with a severe UC phenotype." (PMID 37998910, 2023). "Its absence seems to increase susceptibility to murine experimental colitis, leading to an increase in Candida colonization, and in parallel in humans a severe form of ulcerative colitis is strongly linked to a polymorphism in the gene for Dectin-1 (CLEC7A)." (PMID 26308062, 2015). "Since antifungal therapy ameliorates colitis in Clec7a knockout mice and CLEC7A is associated with the severity of UC in humans, the role of this receptor in patients with non-IgE CMA may play a role in protecting against fungal-induced intestinal inflammation." (PMID 41438035, 2025). "We previously reported that DSS-induced colitis is suppressed in Clec7a–/– mice, because colonization of a regulatory T cell (Treg)-inducing commensal bacterium Lactobacillus murinus is increased in the intestine of Clec7a−/− mice." (PMID 36932082, 2023). "Shortening of colon length, one of the symptoms of colitis, was milder in ApcMin/+Clec7a−/− mice, as observed in DSS-treated Clec7a−/− mice." (PMID 36932082, 2023). "Preclinical mouse models with CLEC7A knock-out or treated with Dectin-1 antagonists suppress the development of colitis through modulating Treg differentiation by modifying the microbiota in the gut70." (PMID 36522454, 2022). "Clec7a-/- mice treated with C. tropicalis exhibited augmented colitis symptoms, IFN-γ, and IL-17 produced by T cells from mesenteric lymph nodes and colons compared with non-treated Clec7a-/- controls." (PMID 35215155, 2022). "Candida tropicalis are pathogenic fungus found in mouse intestine and when SPF mice were colonized with them, Clec7a(−/−) mice developed much severe colitis compared with uncolonized Clec7a(−/−) mice or colonized WT mice." (PMID 32601832, 2021). "When colitis was induced, in all groups, the clear expression pattern of Muc2, Reg3b, and Reg3g was lost, but Clec7a, Clec4n, and Il22 mRNA expression was still increased in HSD- vs. CD-fed mice." (PMID 33339337, 2020). "Mice lacking CLEC7A gene (Dectin-1), thus having dys-regulated interactions with fungal microbiome (mycobiome) show an increased susceptibility to dextran sulfate sodium (DSS) induced colitis." (PMID 30906299, 2019). "It participates in the activation of NF-κB under dectin-1 (C-type lectin domain family 7-member A, CLEC7A) stimulation and interactions between commensal fungi and the c-type lectin receptor dectin-1 influence colitis, which haplotype rs2078178–rs16910631 was found to be associated with CD and UC." (PMID 30008619, 2018).
Candida infection (43 papers, 2009 to 2025). "By contrast, Clec7a–/– animals controlled subcutaneous candidiasis similarly to WT." (PMID 36377664, 2022).
ulcerative colitis (18 papers, 2009 to 2024). An inflammatory bowel disease involving the mucosal surface of the large intestine and rectum. "Interestingly, some CLEC7A polymorphisms associate with severity of ulcerative colitis severity in humans, indicating the relevance of Dectin-1 in the regulation of gut inflammation." (PMID 35237264, 2022). "Moreover, in humans they identified a gene polymorphism for Dectin-1 (CLEC7A) that is strongly linked to a severe form of ulcerative colitis." (PMID 30984184, 2019). "Interestingly, a polymorphism in Dectin1 (CLEC7A) was associated with severe ulcerative colitis (UC) in humans." (PMID 27531998, 2016).
aspergillosis (14 papers, 2010 to 2024). Aspergillosis is an infection, growth, or allergic response caused by the Aspergillus fungus. "Despite genetic replication studies are in general scarce, the link between genetic polymorphisms in PTX3 (rs1840680) and rs7309123 (CLEC7a) and aspergillosis risk have been successfully replicated." (PMID 36733397, 2022). "Individuals suffering from Mendelian defects in Clec7a are usually not affected by aspergillosis, but in the case of allogeneic HSCT, Clec7a polymorphisms (in both donor and recipient genomes) potentiate the chance of pulmonary fungal infection." (PMID 35887412, 2022).
melanoma (14 papers, 2016 to 2025). A malignant, usually aggressive tumor composed of atypical, neoplastic melanocytes. "In patients with triple negative breast cancer and melanoma, elevated levels of the C-type lectin receptor Dectin-1 (CLEC7A), recognizing β-glucans on fungal cells and sensing pathogenic and commensal fungi, were associated with poorer survival." (PMID 38833685, 2024). "The expression levels of Clec7a and Tlr2 were increased in mice treated with T. stromaticum and inoculated with murine melanoma compared to controls only inoculated with melanoma." (PMID 32547964, 2020). "Our results also show that Clec7a levels were 16 times higher in mice treated with both melanoma and T. stromaticum in comparison to treated with only melanoma." (PMID 32547964, 2020). "We revealed that elevated expression of CLEC7A could result in enhanced anti-tumoral immunity and may be correlated with prolonged survival in melanoma." (PMID 33868993, 2021). "Three genes, i.e., CLEC7A, CLEC10A, and HAPLN3 have been reported to exhibit prognostic significance with respect to melanoma for the first time, while HCP5 has been reported to inhibit the development of cutaneous melanoma." (PMID 33868993, 2021). "The four genes (CLEC7A, CLEC10A, HAPLN3, and HCP5) were also identified as meaningful anti-tumoral genes in melanoma." (PMID 33868993, 2021). "Among these, CLEC7A, CLEC10A, and HAPLN3 have not yet been reported to be correlated with melanoma before." (PMID 33868993, 2021).
Obesity (14 papers, 2017 to 2024). Accumulation of substantial excess body fat. "The Clec7a agonist accelerated diet-induced obesity, while Clec7a deficieny in mice resulted in resistance to diet-induced obesity and blocked the anti-obese effect of antifungal drugs and fungi." (PMID 38007451, 2023). "in mice, and Clec7a-deficient mice developed resistance to diet-induced obesity and blocked the anti-obesity effects of antifungal drugs and fungi." (PMID 38007451, 2023). "Moreover, in line with the hypothesis that Clec7a might be associated with obesity, we observed that Clec7a KO mice were resistant to diet-induced obesity." (PMID 38007451, 2023). "The data presented here indicate that Clec7a is required for the occurrence of gut fungus-mediated diet-induced obesity." (PMID 38007451, 2023). "Next, we hypothesized that blockade of fungal recognition, by deleting the Clec7a gene, might confer a similar anti-obesity effect." (PMID 38007451, 2023). "Taken together, these results indicate that gut fungi/Clec7a signaling is involved in diet-induced obesity and may have therapeutic implications as a biomarker for metabolic dysregulation in humans." (PMID 38007451, 2023). "Overall, these results suggest that intestinal fungi/Clec7a signaling is involved in diet-induced obesity and may have therapeutic significance as a biomarker for metabolic disorders in humans." (PMID 38007451, 2023). "The study also identified 3 additional genes CLEC7A, MSRB3, and PEX5L that are common among HCL, obesity, and CVD." (PMID 36035865, 2022).
pancreatic cancer (13 papers, 2018 to 2024). "CLEC7A has been widely studied in pancreatic cancer, kidney cancer, and liver cancer, etc., but the true role of this gene remains controversial." (PMID 35480896, 2022). "CLEC7A encodes dectin, which helps to form the TME and which can suppress CD4+ and CD8+ T cells in pancreatic cancer." (PMID 35783358, 2022).
autoimmune disease (11 papers, 2009 to 2025). A disorder resulting from loss of function or tissue destruction of an organ or multiple organs, arising from humoral or cellular immune responses of the individual to their own tissue constituents. "Clec7a encodes the surface glycoprotein Dectin-1 shown to be involved in phagocytosis, intracellular signaling, and autoimmune diseases, and is also a marker of disease-associated microglia (DAMs)." (PMID 34281628, 2021).
coccidioidomycosis (11 papers, 2017 to 2025). A fungal infection caused by Coccidioides immitis. "Studies of C57BL/6 with Clec7a/DECTIN-1 deletion as well as the cross with DBA/2 mice demonstrated the importance of Dectin-1 in conferring resistance to intranasal coccidioidal infection." (PMID 37233265, 2023).
ischemic stroke (11 papers, 2020 to 2025). A stroke disorder caused by obstruction of blood flow to the brain, due to thrombotic (local blood clot formation) or embolic (due to a blood clot or other material traveling from another site) event. "While Clec7a activation has been shown to exacerbate neuroinflammation in ischemic stroke models, it promotes phagocytosis and synaptic loss in AD models." (PMID 40243488, 2025). "In this study, Clec7a, a pattern‐recognition receptor, is identified as a key trigger of ischemic stroke." (PMID 39088351, 2024). "A recent study demonstrated that Clec7a could exacerbate microglia-mediated synapse elimination, leading to the impairment of neurological function in ischemic stroke." (PMID 39905541, 2025). "While Clec7a is primarily involved in fungal recognition, it was found to have an impact on long-term neurological damage after ischemic stroke, specifically manifested through exacerbating synapse engulfment mediated by microglia, leading to synapse loss and neurological deterioration." (PMID 40723833, 2025). "This discovery indicates the crucial role of Clec7a in ischemic stroke and suggests it may be a potential target for treating ischemic stroke." (PMID 40723833, 2025). "CLEC7A silencing also reduced infarctsize and brain water content in ischemic stroke rats." (PMID 40758965, 2025). "Our experimental data showed that Clec7a is a key factor of ischemic stroke, indicating that therapeutic reduction of Clec7a function might be beneficial for the treatment of ischemic stroke." (PMID 39088351, 2024). "Therefore, Clec7a may serve as a potential therapeutic target for ischemic stroke." (PMID 39088351, 2024).
vulvovaginal candidiasis (11 papers, 2014 to 2025). Infection of the vulva and vagina with a fungus of the genus CANDIDA. "Mutations affecting the C-type lectin receptor (CLR) pathway, including those in CLEC7A (encoding Dectin-1) and CARD9, are strongly associated with increased susceptibility to chronic mucocutaneous or vulvovaginal candidiasis as well as fungal meningitis." (PMID 41249509, 2025). "Defect in the CLR Dectin1, encoded by CLEC7A (C-type lectin domain containing 7A) predisposes humans to invasive aspergillosis (IA), chronic mucocutaneous candidiasis (CMC), and recurrent vulvovaginal candidiasis (RVVC)." (PMID 34490039, 2021).